MIR488 (microRNA 488)
Synonyms: hsa-mir-488; MIRN488; mir-488
Gene: MicroRNA gene on chromosome 1 (177,029,363 to 177,029,445, reverse strand). Ensembl gene ENSG00000202609.
Gene Ontology:
Biological process: miRNA-mediated post-transcriptional gene silencing
Cellular component: RISC complex
Homologues: Orthologues: chimpanzee ptr-mir-488 (99% identical), macaque mml-mir-488 (99% identical), pig MIR488 (98% identical), dog MIR488 (96% identical), rat Mir488 (89% identical), mouse Mir488 (88% identical), rabbit MIR488 (65% identical).